IL1B (interleukin 1 beta)
Diseases named in the same sentence as IL1B in open-access papers (continued):
Sharing a sentence is not in itself a finding about the gene and the disease.
infection (continued). "During the infection process of invasive S. aureus, pathogen-associated-molecules initiate the innate immune system leading to activation and recruitment of neutrophils and macrophages and the production of pro-inflammatory cytokines, most notably TNF-α, IL-1β, and IL-6." (PMID 27917374, 2016). "However, by comparison, the role of IL-1β and IL-18 in this infection has been somewhat neglected and remains unclear." (PMID 25768794, 2015). "Furthermore, CRP is produced and secreted by signaling hepatocytes in response to proinflammatory cytokines such as IL-1β and IL-6 and the lag time from the onset of infection until CRP elevation is 6 to 8 hours, possibly interfering with the usefulness of this measurement." (PMID 25667565, 2015). "Finally, the il1b gene expression was up-regulated after 1 and 15 days of infection." (PMID 26691348, 2015). "Thus the transition from promastigotes to amastigotes during infection may be of the essence for a Leishmania-mediated effect on IL-1β maturation." (PMID 26114647, 2015). "Thus, we sought to assess whether it is sufficient to block IL-1β signaling only during the course of infection, an important determinant regarding a potential therapeutic intervention." (PMID 24918427, 2014). "However, IL-1β neutralization had a distinct effect on infection and lung inflammation." (PMID 25500839, 2014). "Since the elevated levels of systemic proinflammatory cytokines (MCP-1, IL-1β, and IL-6) and increased peripheral blood leukocyte counts have been reported in obese humans and CPEfat/fat mice, we assessed these cytokines in serum and peripheral blood leukocyte counts after infection." (PMID 25203099, 2014). "Furthermore, the antibody array was randomly confirmed by qRT-PCR, and the results showed that pro-inflammatory chemokines including CCL5 and CCL2 and cytokines including IL-6, IL-1β, IL-12, and IL-17 were significantly enhanced after infection with aG and CTN." (PMID 25182681, 2014). "In addition, the IL1B-31TT and IL8-251 TT genotypes seem to act as protective factors against H. pylori infection while IL8-251TA genotype may be a risk factor for infection with this bacterium." (PMID 24803922, 2014). "Therefore, treatment with anti-IL-17A seems to be favorable in the early phases of exacerbations while blocking IL-1β might be more advantageous during the ongoing infection." (PMID 24918427, 2014). "Interestingly, infections in caspase-1/11 deficient mice showed no defect in bacterial clearance, suggesting that the protective IL-1β response in the lung can arise independently from these inflammasomes." (PMID 25198773, 2014). "Thus, we propose that BsaK is essential for early caspase-1-dependent macrophage death and IL-1β release, whereas other bacterial factors or mechanisms might contribute to caspase-1 activation in the late phase of infection." (PMID 24626296, 2014). "In addition, absent caspase-1 processing by ΔBsaK and ΔFliCΔBsaK was attendend by significantly reduced secretion of IL-1β six hours after infection, whereas a similar IL-1β production could be detected 24 hours after infection." (PMID 24626296, 2014). "The differential expression level of MR may determine the differential infection rate because of its strong binding to DV, while the distinct regulation of inflammasome activation in M-Mφ and GM-Mφ contribute to the differential production of IL-1β and IL-18." (PMID 23742038, 2013). "Despite the fact that IL-1β signaling also is critical for innate immune responses to Mtb in these animal models, it would appear that they would not be appropriate for in vivo modeling of the modulatory effects of vitamin D on the early innate immune responses to infection." (PMID 23762029, 2013). "Here, we investigated the influence of vIL-1βR on blocking interleukin-1beta (IL-1β) upon MVA infection in various antigen presenting cells of murine and human origin, and analyzed whether inflammasome function contributes to IL-1β production in different cell types." (PMID 23356675, 2013).
infection (continued). "Therefore, we tested whether the infection of the iacP mutant strain expressing two flagellin subtypes (FljB and FliC) could induce the release of proinflammatory cytokines such as IL-18 and IL-1β in the RAW 264.7 macrophage cell line." (PMID 24069357, 2013). "Importantly, most of the Mtb-infection induced IL-1β, IL-6, TNF-α and MCP-1 network genes were down regulated by PZA-treatment at both 42 and 63 days, while only 8–10% of these pro-inflammatory network genes were up-regulated, in all the four pro-inflammatory networks at both time points." (PMID 24015316, 2013). "To characterize the mechanism underlying the IL-1β response in NHBE cells, we measured receptor transcript levels; we also assessed the efficiency of specific knockdowns of TLR3, RIG-I, and NLRP3 in primary NHBE cells at 13 h post-infection (time of peak transcriptional response to IAV)." (PMID 23592984, 2013). "Thus iSCs elaborate IL-1β and IL-33 protein in response to infection with live Salmonella." (PMID 24137162, 2013). "However, mice singly deficient for either IL-1α or IL-1β survived for the duration of the acute M. tuberculosis infection study (3 months) without clinical symptoms of infection." (PMID 25400917, 2013). "Mice double deficient for IL-1α plus IL-1β could not control the infection, similar to IL-1R1 deficient mice on day 35 post-infection, although bacterial burdens were not as high as those reached in TNF KO mice which succumbed at 4 weeks." (PMID 25400917, 2013). "Infection of NHBE cells by HRV is thus likely associated with recognition of viral products, oligomerisation of the inflammasome resulting in caspase-1 activation and release of mature IL-1β and IL-18, but also an alternative active process resulting in IL-1α release." (PMID 23723976, 2013). "To determine whether post-transcriptional control of IL-1β could account for the observed differences in IL-1β secretion in the supernatants, we profiled the expression of pro-IL-1β in whole cell lysates of macrophages at 6 h and 24 h post-infection by western blot." (PMID 23849220, 2013). "Although IL-1β is the major cytokine that induces IL-1R/MyD88-dependent neutrophil recruitment during a S. aureus skin infection, the source and kinetics of IL-1β production during an infection in vivo has remained unknown." (PMID 23209417, 2012). "To investigate whether induction of IL-1β secretion by B. cenocepacia-infected macrophages depends on a specific secretion system, we performed infections with mutants carrying partial or complete deletions in the genes encoding each of these secretion systems that render them nonfunctional." (PMID 22848580, 2012). "Neutrophil-derived IL-1β may also promote other immune responses at the site of infection." (PMID 23209417, 2012). "While it is tempting to speculate that these adoptively transferred IL-1β-producing neutrophils directly rescued the neutrophil recruitment response at the site of infection, it is also possible the low levels of IL-1β acted indirectly and/or through another anatomical site such as the blood." (PMID 23209417, 2012). "Furthermore, our in vitro infection experiments used highly purified mouse neutrophils separated with anti-Ly6G MACS magnetic beads (99.1% pure with only 0.1% monocytes) to ensure that we were evaluating neutrophil specific production of IL-1β." (PMID 23209417, 2012). "However, a different situation occurs in infection and inflammation where an upregulation of inflammatory IL-1b might contribute to the injury of testicular tissue." (PMID 22558148, 2012). "To exclude that the large variation in il1b and mmp9 induction found after immersion might be due to individual variation in responsiveness of different embryos, we decided to compare the immersion system with intravenous infection." (PMID 22003892, 2011).
infection (continued). "However, in other infections and in models of sterile inflammation, caspase-1 seems to be less important, and alternative mechanisms such as neutrophil-derived serine proteases or proteases released from microbial pathogens can process and activate IL-1β." (PMID 20195505, 2010). "Treatment of THP-1 cells with caspase-1 inhibitor, zVAD-fmk, alone caused no induction of IL-1β but when combined with the infection with vMyxM013-KO virus resulted in the dramatic inhibition of IL-1β secretion at early time points, starting in the first hour post-infection." (PMID 19851467, 2009). "Additionally, in our study, elevated IL-1β levels were significantly associated with chronic trachoma cases but not with infection." (PMID 18628987, 2008). "Here we have shown that after infection of non-vaccinated Tlr4-deficient mice the number of bacteria, and lung IL-1α and IL-1β expression are higher than in similarly treated wild-type controls, while bronchial LN cell IFN-γ and IL-17 production and splenocyte TNF-α production are lower." (PMID 18498620, 2008). "The abundance of Enterobacteriaceae or Escherichia-Shigella was positively correlated with rectal temperature at 12 and 24 h post-infection, serum TNF-α level, and jejunal IL-1β, IL-10, and TNF-α mRNA levels." (PMID 41547922, 2026). "The abundance of Proteobacteria exhibited a positive correlation with rectal temperature at both 12 and 24 h post-infection, as well as with serum TNF-α levels and jejunal IL-1β and TNF-α mRNA levels." (PMID 41547922, 2026). "IL-17 stimulates the production of other pro-inflammatory cytokines, such as IL-6, IL-1β, and TNF-α, and induces the production of chemokines that recruit neutrophils to the site of infection, amplifying the inflammatory response." (PMID 40145967, 2026). "While IL‐1β, TNF‐α, and IL‐6 exhibited a declining trend following the initial peak within 72 h, implying potential resolution of the initial infection, the trajectory of HMGB1 levels remained inconspicuous and even continued to rise in the spleen until 72 h." (PMID 41551210, 2026). "Key proinflammatory cytokines-interleukin (IL)-1β, tumor necrosis factor (TNF)-α, and interferon (IFN)-γ-were elevated in the cecum during early infection but declined in the spleen during later phases." (PMID 42204750, 2026). "Infection activates the NLRP3 inflammasome via ROS, cathepsin B, and potassium efflux, promoting IL-1β/IL-18 secretion and ASC oligomerization." (PMID 42245999, 2026). "During early kidney injury, M1 macrophages, induced by IFN‐γ and pro‐inflammatory signals, highly express iNOS and CD86, releasing IL‐1β, IL‐6, and TNF‐α to combat infection." (PMID 41527491, 2026). "The cytokine storm refers to the excessive activation of the immune system following infection, resulting in the massive release of various inflammatory cytokines, such as tumor necrosis factor‐alpha (TNF‐α), interleukin (IL)‐1β, and IL‐6." (PMID 41551210, 2026). "The IL1B gene was significantly downregulated preferentially in CDV Ond-infected AMs as shown by RT-qPCR and RNA-seq analyses of the AMs during the initial infection phase." (PMID 41405202, 2026). "Unexpectedly, ΔespL infection triggered comparable GSK’872-sensitive macrophage cytotoxicity and IL-1β release between WT and Ifnar1−/− macrophages, suggesting that autocrine type I IFN signalling is dispensable for ΔespL-induced necroptosis." (PMID 40128366, 2025). "At a multiplicity of infection (MOI) of 30, Ad5-IκBαΔN maximally inhibits NF-κB-dependent transcription induced by IL-1β." (PMID 41359631, 2025). "The concentration of chemokines CxCL1/KC/GRO-α, CxCL2/MIP-2, CCL5/RANTES and cytokines TNF-α, IL-1β, IFN-γ, IL-5, IL-6, IL-9, IL-10, IL-13, IL-17, IL-23 circulating in blood were measured in experimental animals on day 15 post-infection." (PMID 40445994, 2025).
infection (continued). "The chemotactic agents CXCL9 and CXCL10 attract cells to the infection site, which secrete more pro-inflammatory cytokines, such as TNF-α, IL-1β and IFN-γ, amplifying the process and exacerbating the Th1 response." (PMID 40608568, 2025). "Offspring of HFD-fed dams exhibited significantly blunted cytokine and chemokine responses during infection, including reduced levels of serum GM-CSF, TNF-α, IL-1β, IL-6, IL-10, and MCP-1 and peritoneal G-CSF, IL-6, and MCP-1." (PMID 40766470, 2025). "The results indicated that 24 h post-infection (MOI 1:1), there was a significant increase in the production of TNF-α, IL-1β, and IL-10 compared to that in the control group." (PMID 40005637, 2025). "This preceded the transcriptional upregulation of inflammatory cytokines, including IL-1β, IL-6, IL-18, and TNF-α, which only became prominent at 12-24 hours post-infection." (PMID 41281739, 2025). "The IL-1β, IL-18, and TNF-α protein levels were increased in the infection group compared with the control group (p < 0.001)." (PMID 40305201, 2025). "Infection of iMGs with single-cycle HIV-1 (Lai∆envGFP/G) also resulted in robust infection and led to significant IL-1β production which was abrogated upon EFV pretreatment, suggesting that viral spread was not required for IL-1β secretion." (PMID 40920844, 2025). "Stimulation of piglets with weaning stress or pathogen infection leads to increased expression and secretion of pro-inflammatory factors IL-6, TNF-α and IL-1β." (PMID 40351768, 2025). "Four weeks post infection with M.tb HN878, we observed a significant increase in circulating IFN-γ, TNF-α, IL-1β, IL-2, IL-6, IL-12p70, IL-17A/F, IL-15, and IL-33 levels in mice immunized with ID93+EmT4TM compared to saline controls." (PMID 40285479, 2025). "When we compared the expression of inflammatory cytokine response of adult and pediatric cells upon HMPV and RSV infection, we observed that adult cells produced more pro-inflammatory cytokines (IL-1β, IL-6, IL-8, and TNF-α) following infection." (PMID 40143308, 2025). "We analysed mRNA expression of 9 inflammatory markers (TGF-β1, TNF-α, IL-1β, IFN-γ, IL-6, IL-23, IL-17a, iNOS and ColA1) in kidney of experimental mice at 15 days post infection." (PMID 40445994, 2025). "At the same time, in infection experiments using cagA+ and cagA− H. pylori strains in 2021, the expression levels of NLRP3, ASC, IL-1β, and IL-18 were higher as a result of cagA+ H. pylori infection compared to cagA− strains." (PMID 40563885, 2025). "The heightened infection risk in GD may be attributable to dysfunction of immune cells, including monocytes, macrophages, dendritic cells, T cells, and B cells, as well involvement of cytokines, such as MCP1/CCL2, CXCL8/IL8, CXCL1, IL-1β, IFNγ, and TNFα, are implicated in GD progression." (PMID 40980139, 2025). "K. pneumoniae infection triggered transcriptional upregulation of IL-1β, IL-6, IL-8, and TNF-α within 2 h post-infection, preceding significant changes in ferroptosis markers." (PMID 41343264, 2025). "Results showed elevated levels of pro-inflammatory cytokines such as TNF-α, IL-6, IL-1β, and chemokines CCL5 (RANTES), and IP-10 (CXCL10) after infection with rHPh-TX H5N1." (PMID 40712003, 2025). "Consistent with the cell infection assay results, K247Q demonstrated the highest levels of proinflammatory cytokines TNF-α, IL-6, and IL-1β, particularly when compared to those produced by K247R at 24 h.p.i." (PMID 40167330, 2025). "At 48 h post-infection, U937 macrophages infected with LRV-1+ isolates exhibited elevated concentrations of TNF-α and IL-1β and reduced IFN-γ, compared to those infected with LRV-1− isolates." (PMID 41471220, 2025). "Further examination of protein levels of inflammatory cytokines (TNF and IL-1β) and chemokines (MCP-1) at day 2 post-infection showed significantly reduced levels of these mediators in TLR7−/− lungs compared to control lungs." (PMID 40162785, 2025).
infection (continued). "Western blot results showed that infection significantly upregulated the expression of HIF-1α and IL-1β, suggesting activation of hypoxic stress and the NF-κB pathway." (PMID 40867552, 2025). "We also detected inflammatory cytokines such as MCP-1, IL-6, IFN-β, and IL-1β in the serum of the CVB3-infected mice, with the results showing that these cytokines were highly expressed post-infection." (PMID 41356483, 2025). "In this review, we focus specifically on how maternal immune activation (MIA) — induced by infections, autoimmune diseases, or other immune challenges during pregnancy — affects fetal brain development via the P2X7/NLRP3/IL-1β signalling axis." (PMID 40713568, 2025). "Infection with 103 TCID50 of PRV-GXLB-2013 resulted in significantly elevated levels of TNF-α, IL-1β, IL-6, IL-8, and MLKL in brain tissues, serum, and C8-D1A cells, compared to the control group (p < 0.01)." (PMID 40732040, 2025). "Several studies indicate an upregulation of myeloid differentiation primary response (MYD) 88-related signaling pathways upon infection of AlvMφ in vitro, leading to increased expression of cytokines (e.g., TNF-α, IL-1β, IL-8, IL-10) and chemokines." (PMID 39796262, 2025). "Infection of monocytic THP-1 cells with CFT073ΔtcpC + pASK-IBA5plus-TcpC, which was induced with increasing Atc concentrations, revealed that IL-1β and to a lower extent TNFα secretion was significantly and dose-dependently augmented." (PMID 41310197, 2025). "Following this, the role of EGR1 in the inflammatory response was further assessed by measuring the level of IL-1β produced by EGR1KO and EGR1WT macrophages during infection." (PMID 41188240, 2025). "Injury and infection activate immune cells, release inflammatory mediators (e.g., TNF‐α, IL‐1β), affecting the excitability of nerve fibers, promoting pain signal generation." (PMID 41395451, 2025). "In infected digitoxin-treated cells, IFN-β, CXCL-10, IL-1β, and IL-8 levels are significantly reduced, suggesting that nuclear α3 modulates IE1-PML early during infection." (PMID 40143325, 2025). "Pa-STING vaccination also significantly reduced levels of IL-1β, IL-6, and TNF-α in the bronchoalveolar lavage (BAL) fluid 20 hours after infection." (PMID 40705476, 2025). "The production of IL-1β and TNF-α was also influenced by the presence of copper during infection with the MtbΔctpA mutant strain." (PMID 40002852, 2025). "PD-1 can reduce levels of inflammatory cytokines, including TNFα, IL-1β, IL-6, and iNOS, suggesting that an increase in eosinophil numbers may act to reduce inflammation and tissue damage induced by catheterization and infection, consistent with our observations here of eotaxin effects during CAUTI." (PMID 40980878, 2025). "From the perspective of the color scale, the expressions of IL-8, IL-1β, IL-4, IL-6, IL-2, TNF-α, IL-10, and IL-17 showed a significant upward trend as the infection duration increased." (PMID 41165313, 2025). "Nonetheless, elevated IL-1β and TNF-α levels have been reported in the later stages of infection with virulent PRRSV strains, and HP-PRRSV is known to induce systemic cytokine responses, including TNF-α, IFN-α, IL-1, and IL-6, around 7 dpi." (PMID 40630508, 2025). "Compared to the control group, the protein expressions of TNF-α, IL-1β, and IL-6 in the GPS infection group were significantly higher (p < 0.01)." (PMID 40867785, 2025). "In the present study, the mRNA expression of IL-1β and TNF-α was upregulated in the brain of CLEC12A−/− mice upon infection." (PMID 41214106, 2025). "In the present research, at 28 days post-infection, CD11d expression was markedly elevated in cardiac tissue, whereas levels of TNF-α, IL-1β, and IL-18 remained within the normal range." (PMID 41472298, 2025). "In the infection of THP-1 cells with the NcGRA7KO parasite, decreased IL-1β release was observed compared with Nc1 infection." (PMID 41357231, 2025).